PLK1 (polo like kinase 1)
Diseases named in the same sentence as PLK1 in open-access papers (continued):
Sharing a sentence is not in itself a finding about the gene and the disease.
cancer (continued). "Increasing evidence suggests that targeting upstream regulatory factors such as histone deacetylase (HDAC), phosphoinositol 3-kinase (PI3K), polo-like kinase 1 (PLK1) and BET bromodomain can lower MYC protein levels and inhibit MYC-driven cancer growth." (PMID 40229260, 2025). "Despite being known for its potential among other PLK types (PLK2, PLK3, PLK4, and PLK5), PLK1 is determined recently as a potential oncogenic target across various cancer types due to its extensive research exploration and essential mitotic roles." (PMID 41404416, 2025). "Constitutive overexpression of PLK1 leads to CIN and aneuploidy, which are salient features of most cancers." (PMID 40347943, 2025). "Both proteins have been previously targeted in human cancers, with multiple AURKB and PLK1 inhibitors gaining FDA approval." (PMID 40149290, 2025). "Mechanistically, PLK1 stabilizes BTB domain and CNC homolog 1 (BACH1), which serves as a crucial transcription factor for genes involved in cancer metabolism and metastasis." (PMID 41284701, 2025). "Since tumor cells upregulate genes such as PLK1, identifying SDL interactions is valuable for identifying new therapeutic targets for cancer treatment." (PMID 40347943, 2025). "It has been found that mitotic kinases, such as polo-like kinase 1 (PLK1) and aurora kinases, are often overexpressed in many different cancers." (PMID 40244152, 2025). "PLK1 and KIF20A are involved in cytoplasmic segregation during mitosis and contribute to cancer cell proliferation." (PMID 40612352, 2025). "Both mechanisms are potentially operative in most cancer cells, where IGF2BP2 inhibition decreases PLK1 expression." (PMID 40347943, 2025). "Recent studies have found that dual-target inhibitors targeting PLK1/BRD4 and PLK1/MEK can produce cumulative effects and exert long-term inhibitory effect on cancer cell growth." (PMID 40612941, 2025). "For example, volasertib can cause downregulated BCL2L1 expression, disrupt the interaction between PLK1 and NEK7, or displacement of HMGB2 from mitotic chromosomes, thereby affecting mitotic arrest and apoptosis in cancer cells." (PMID 39872221, 2025). "Interestingly, our retrospective analysis of the DepMap database revealed significantly higher expression of PLK1 in cancers with FA pathway disruptions compared with cancers with intact FA pathway, suggesting that FA pathway disruption may lead to PLK1 “addiction”." (PMID 40111122, 2025). "Further studies have found that the activation of PLK1 inhibits the expression of TNF-induced cyclin D1, providing a potential mechanism for TNF-α’s involvement in inflammation-induced cancer." (PMID 40612941, 2025). "Recent studies indicate that downstream genes of the DREAM complex, such as FOXM1, PLK1, and AURKA, are critical for cancer cell proliferation across various cancers." (PMID 39796178, 2025). "Polo-like kinase 1 (PLK1) is a key regulator in mitosis and a highly potent target for anti-cancer therapies." (PMID 40852028, 2025). "Several PLK1 inhibitors have been extensively studied, and BI6727, in particular, has entered phase III clinical trials, offering new hope for cancer treatment strategies." (PMID 40809688, 2025). "A surface-entropy reduction approach for human Polo-like kinase 1 (PLK1) enabled a reproducible and robust crystallization system for this cancer drug target." (PMID 41246821, 2025). "Interestingly, the ability of plk1 to couple with cell signaling pathways commonly associated with cancer development appears to be gathered in the non-mitotic cell cycle span, while all plk1 functions in mitosis are generally connected to cancer through possible genomic instability events." (PMID 40430225, 2025). "In a prostate cancer study, monensin was found to bind to the DNA-binding domain (DBD) of FOXM1, reducing its interaction with downstream target genes such as PLK1 and CDC25B, thereby exerting an anti-cancer effect." (PMID 40612352, 2025).
cancer (continued). "CCNB1, PLK1, CDK1, BUB1B, AURKA, and NDC80 are genes involved in various stages of the cell cycle process, which is crucial from a cancer perspective." (PMID 40287845, 2025). "The protein expression levels of PLK1, SLC2A1, ANGPTL4, and CDKN3 in LUAD tissues were all significantly higher than those in para-cancer tissues." (PMID 38345559, 2024). "PLK1 and AURKA are commonly overexpressed and are recognized as promising therapeutic targets in a wide range of cancers, including for SCLC." (PMID 39085197, 2024). "We further revealed that inhibitors targeting the Src, Mcl‐1, STAT3, BRD4, p300, PLK1, or class I HDACs significantly enhanced CDK9i‐induced cell death in various KRAS‐mutant cancers." (PMID 39254172, 2024). "Overexpression of PLK1 also promotes EMT and can promote motility and invasiveness in diverse types of cancer like breast, prostate, and colorectal cancer." (PMID 38886738, 2024). "Since CDK1, CHEK1, KIF11, PLK1 and TTK was significantly elevated with cancer progression in LUAD and exhibited excellent binding performance with 6-MDS, they were chosen for further validation." (PMID 38783288, 2024). "Overall, the interaction between PLK1 and APC in cancer cells is complex and can have both tumor-promoting and tumor-suppressing effects, depending on the context." (PMID 39273409, 2024). "Although WEE1, PLK1, and AURKA kinase inhibitors have been studied in HNSCC and other cancers, small molecule inhibitors targeting other G2/M kinases such as TTK are currently in preclinical or clinical development." (PMID 39392349, 2024). "PLK1 also controls several key transcription factors that promote cell proliferation, transformation, and EMT in various types of cancers, including CRC." (PMID 39273409, 2024). "In this study, we identified polo-like kinase 1 (PLK1) as a novel kinase of RhoGDI1 and investigated the molecular mechanism by which the interaction between RhoGDI1 and PLK1 regulates cancer cell migration." (PMID 38355643, 2024). "The data demonstrate that PLK1 and NUF2 are the most essential genes among these cancers, with the lowest Chronos scores." (PMID 39392349, 2024). "Plk1 is a major regulatory factor in mitosis and is upregulated in cancer cells such as human breast (MCF-7) and melanoma (A375) cancer." (PMID 38951806, 2024). "Previous studies have shown that PDK1 can activate the PI3K/Akt/mTOR pathway to promote tumor proliferation and invasion; Additionally, phosphorylation of PDK1, an upstream regulator of C-Myc, activates PLK1-MYC signaling and promotes cancer proliferation." (PMID 38671369, 2024). "Regarding cancer biomarkers, Ki67, MMP2, and MMP9 protein levels were decreased by SAMD5 but increased by PLK1; PLK1 overexpression significantly alleviated the inhibitory effects of SAMD5 on these factors." (PMID 39524172, 2024). "It is noteworthy that both BRD4 and PLK1 play important roles in mitosis, as well as the finding that inhibition of BRD4 and PLK1 can sensitize cancer cells to DNA-damaging agents such as radiation and chemotherapy drugs." (PMID 37765111, 2023). "In this study, we found a positive correlation between the expression of UBE2C and PLK1/BIRC5 in the Cancer Genome Atlas (TCGA) database, revealing a potential combination therapy candidate for pan-cancer." (PMID 37958642, 2023). "Depmap database was used to explore genome-wide knockout library screening data, and pan-cancer analysis of DAP3, PPP2R5B, PLK1, and GSDME genes on cancer cell growth." (PMID 37415742, 2023). "Here, we show that AHR is a direct substrate of PLK1 and that phosphorylation of AHR in LUAD promotes epithelial–mesenchymal transition (EMT) to enhance the metastatic potential of cancer cells." (PMID 37988371, 2023). "The results showed that CCNA2, CDK1, KIF11, MKI67, and PLK1 were significantly and positively correlated with CEP55 in pan-cancer." (PMID 37887301, 2023). "Therefore, PLK-1 may act as a promising target for the therapeutic cure of various cancers." (PMID 37570823, 2023).
cancer (continued). "In this study, after the pharmacological combined inhibition of PLK1 and ACLY, the mRNA expression levels of SREBF1 and MYC were significantly decreased in most pan-cancer cell lines." (PMID 37958642, 2023). "Since CDC25C is the link among CDK1, CCNB, and PLK1, and the expressions of CDC25C among ten cancer cell lines are also downregulated, we added CDC25C for the experiment validation step." (PMID 37007025, 2023). "To understand the regulatory mechanism of FOXM1a in cancer cell proliferation and tumorigenesis, we analyzed the effects of FOXM1a on the expression of FOXM1c target genes, including CDC25B, PLK1, and CCNB1, which are essential for cell proliferation." (PMID 37759731, 2023). "Using Timer 2.0, we found that PLK1, CDK1, CCNB1, and CCNB2 were upregulated in different cancer types compared with normal samples from the TCGA data set." (PMID 37007025, 2023). "Survivin, an IAP family member and substrate of PLK1 and AURKB, is involved in carcinogenesis, tumor progression, cancer cell proliferation, inhibition of apoptosis, neoangiogenesis, and drug resistance." (PMID 36627281, 2023). "In this study, the effects of DAP3, GSDME, PLK1, and PPP2R5B knockdown on cancer cell growth were analyzed by DepMap, a cancer survival-dependent gene database." (PMID 37415742, 2023). "Our study reveals the potential mechanisms through which cell-cycle-related genes regulate metabolism and proposes a potential combined targeted therapy for patients with higher PLK1 and ACLY expression in pan-cancer." (PMID 37958642, 2023). "In summary, we identified a new UBE2C/PLK1-ACLY axis that plays an essential role in the cell cycle and pan-cancer cells." (PMID 37958642, 2023). "The hit list in our screen reassuringly contained many well-known cancer genes such as PCNA, CDK1 and PLK1, further demonstrating the validity of the screen results." (PMID 37161535, 2023). "Our present study first examined the effects of the pharmacological combined inhibition of PLK1 and ACLY on the cell proliferation and clone formation of several cancer cell types." (PMID 37958642, 2023). "But at the same time, we found that the other two inhibition combinations, PLK1 combined with IDH1 and IDH1 combined with ACLY, were less effective in inhibiting the malignant phenotype of pan-cancer cell lines." (PMID 37958642, 2023). "Other molecules, such as FOXA1, SETD2, Hes5, C/EBP-δ, PRMT5, METTL3, Piwil1, PLK1, ERK1/2, and a series of miRNA, indirectly modulate the sensitivity of cancer cells to drugs by regulating FBXW7." (PMID 36998461, 2023). "Various studies have shown that the cell-cycle-related regulatory proteins UBE2C, PLK1, and BIRC5 promote cell proliferation and migration in different types of cancer." (PMID 37958642, 2023). "According to the Oncomine and TCGA data, PLK1, CDK1, and CCNB are known to be elevated in different cancer types." (PMID 37007025, 2023). "Overall, PLK1 blockage enhanced KRASG12Ci efficacy in KRASG12C-mutant tumors, delayed cancer progression and counteracted drug resistance." (PMID 38104151, 2023). "PLK-1 is a crucial component of the PLK family, which leads to various cancers including lung cancer." (PMID 37570823, 2023). "Several of the hits in our screen (such as PLK1 and CDK1) have previously been labelled as “core essential”, “fitness genes” or “pan-cancer” genes, as they are considered essential for all cells (cancer and healthy cells) to function." (PMID 37161535, 2023). "Next, we analyzed the expression levels of UBE2C and PLK1 in different pathological stages and found that UBE2C was significantly overexpressed in stage III and IV in 17 types of cancers." (PMID 37958642, 2023). "All these suggested that PLK1 promoted the stability of c-Myc protein, and in turn, c-Myc directly enhanced PLK1 transcription, establishing a positive feedback circuit in KRAS-mutant cancer cells." (PMID 38104151, 2023).
cancer (continued). "PLK1 and MYC create a positive feedforward activation loop that sustains a high expression, and PLK1 inhibitors induce apoptosis in MYC-overexpressing tumor cells, highlighting their potential as therapeutics for MYC-dependent cancers." (PMID 37755397, 2023). "Oncogenes, such as MET, PLK1 and CCNE1, demonstrated higher expression levels in cancer tissues than in normal tissues in the TMA and TCGA data sets." (PMID 36137139, 2022). "PLK1 is a key mitotic kinase that is overexpressed in various cancers including NSCLC and drives cancer growth." (PMID 35871223, 2022). "Therefore, PLK-1 may be a clinically valuable target for cancer treatment." (PMID 36457496, 2022). "Polo-like kinase 1 (PLK1) is a critical mitotic kinase that is overexpressed in various cancers, including NSCLC, and drives cancer growth." (PMID 38091511, 2022). "For example, Polo-like kinase 1 (PLK1), a critical target of miR-100, can prevent cancer progression and regulate the proliferative activity in early PDAC when overexpressed." (PMID 35205236, 2022). "PLK1 is a Serine/Threonine protein kinase of the CDC5/Polo subfamily and a critical cell cycle regulator frequently overexpressed in cancers." (PMID 36293001, 2022). "The correlation heatmap showed the top five genes (CCNA2, CKAP2L, KIF11, MKI67 and PLK1) that were positively and significantly related to RRM2 in almost all TCGA cancers." (PMID 35740608, 2022). "PLK1 is a key cell-cycle regulator, as well as an activator of MAPK signaling; activation of the PLK1 pathway has been found in a variety of human cancers." (PMID 36009461, 2022). "For example, PLK1 is a key mitotic kinase that is overexpressed in various cancers, including NSCLC, and drives cancer growth." (PMID 38091511, 2022). "Then, to finalize the genes and protein products in question, we evaluated the crucial genes in the GEPIA database and finally confirmed MYLK, SOCS3, STAT5B, BIRC5, PLK1, and RAPGAP1 proteins significantly in this cancer database." (PMID 35928368, 2022). "Furthermore, targeting PLK1 activation may be a therapeutic approach for cancer treatment 44-46." (PMID 36439881, 2022). "The results showed that higher PLK1 mRNA levels were statistically related to poorer OS and DFS in pan-cancer." (PMID 36618405, 2022). "PLK1 is the most widely studied member of the PLK kinase family and is primarily involved in cell cycle regulation and cancer development." (PMID 36299451, 2022). "Of these DEGs, 6 (EGFR, GATA3, DIABLO, CFLAR, RIPK3, and MAPK8) were repressed, while (ZBP1, PLK1, SPATA2, BCL2, ALK, FASLG, TNFRSF21, and LEF1) were upregulated in cancer cases." (PMID 35610275, 2022). "Currently, polo-like kinase 1 (PLK1), a protooncogene, is one of the anti-cancer drug targets and has been extensively studied due to its role in cancer development." (PMID 35372354, 2022). "Consistent with BRCA results, a total of 25 cancers, FAM83D expression levels strongly correlated with PLK1." (PMID 36568373, 2022). "We have recently shown that dual inhibition of PLK1 and FGFR1 has synergistic anticancer effects in KRAS-mutant cancer cells, as FGFR1 and PLK1 cooperate control the metabolic stress associated with KRAS mutation." (PMID 36483040, 2022). "The abnormal expression of Plk1 and AURKA is proven to be toughly related to the tumorigenesis of many cancer types." (PMID 35656338, 2022). "The combination of CDK1/ERK2/PLK1 and CEP55 inhibitors is a rational strategy to impair cell cancer division and merits further investigation." (PMID 35517890, 2022).
cancer (continued). "Very recent well written reviews have been published on PLK1 structure, regulation and its role in cancer development and therapy, and here we summarize some key features of the PLK1 protein that could help clarifying the rationale for the design of PLK1 inhibitors and their potential side effects." (PMID 35719948, 2022). "Several oncogenic targets of STAT3 have been recently identified such as c-myc, c-Jun, PLK-1, Pim1/2, Bcl-2, VEGF, bFGF, and Cten, and inhibitors of STAT3 have been developed for cancer prevention and treatment." (PMID 33435349, 2021). "Targeting the diverse functions of PLKs (tumor suppressor, oncogenic) are currently at the center of numerous investigations in particular with the inhibition of PLK1 and PLK4, respectively in multiple cancer trials." (PMID 34065956, 2021). "Polo-like kinase 1 (PLK1), an essential cell cycle regulator and a member of the serine/threonine-protein kinase family, is overexpressed in various human cancers." (PMID 34565365, 2021). "Polo-like kinase 1 (PLK1) plays an important role in cell cycle progression and proliferation in cancer cells." (PMID 33917995, 2021). "To further evaluate the biological and inhibitory effects of NSC765600 and NSC765691 in cancer, we identified CCND1/CDK4/PLK1/CD44 as potential druggable candidates for both compounds by using online prediction tools." (PMID 34063946, 2021). "BORA activates the key mitotic PLK1 function as a prerequisite for mitotic entry and G2/M checkpoint recovery and high BORA correlates with increased cancer cell proliferation and high grade of chromosomal instability." (PMID 34065956, 2021). "Similar to PLK1/2, PLK3 was involved in regulation of cell cycle progression, and it acted as a cancer suppressor in several types of malignancies." (PMID 34080290, 2021). "While it has been thought that colchicine is too toxic for cancer therapy, benzodioxole-containing compounds such as LI, which target colchicine-binding sites, may offer an anti-microtubule therapeutic strategy with reduced side effects, when combined with other drugs such as anti-Plk1 inhibitors." (PMID 34493069, 2021). "PLK1 is the prototype of the PLK family with a well-defined role in cell cycle progression and cancer while PLK4 is important in centrosome dynamic during the cell cycle." (PMID 33842469, 2021). "This was in part due to increased Aurora A and PLK1 activity, that are also found upregulated in the FGFR1-driven cancers." (PMID 34207779, 2021). "PLK1 inhibitors have been developed and approved by FDA as Orpha Drug Designation for cancer therapy." (PMID 34503297, 2021). "Using bioinformatics, we successfully identified CCND1/CDK4/PLK1/CD44 as oncogenic signatures, which drives cancer progression and resistance to treatment, and as potential druggable candidates for both NSC7565600 and NSC765691 small molecules." (PMID 34063946, 2021). "Multiple studies have shown that PLK1/ERK is a key pathway to induce malignant transformation and tumor formation of cancer cells." (PMID 34880385, 2021). "Several genes, including CCNB1, CDC20, CDC6, PLK1, and PTTG1, had multiple roles as core essential genes, oncogenes, and roles as hallmarks of cancer and in KEGG pathways." (PMID 32040444, 2020). "Co-delivery of PLK1-shRNA and DOX was also reported to provide the synergistic effect in treatment of cancer in nude mice due to the antitumor effect of DOX and ability of PLK1-shRNA to silence PLK1 expression for higher apoptosis effect." (PMID 32083052, 2020).